TPRKB (TP53RK binding protein)
Description:
Component of the EKC/KEOPS complex that is required for the formation of a threonylcarbamoyl group on adenosine at position 37 (t(6)A37) in tRNAs that read codons beginning with adenine. The complex is probably involved in the transfer of the threonylcarbamoyl moiety of threonylcarbamoyl-AMP (TC-AMP) to the N6 group of A37. TPRKB acts as an allosteric effector that regulates the t(6)A activity of the complex. TPRKB is not required for tRNA modification.
Synonyms: CGI-121; CGI121; GAMOS5
Tractability: Small molecule: a structure with a bound ligand is known; it has a high-quality binding pocket. PROTAC: ubiquitination databases record sites on it; its protein half-life has been measured.
Gene: Protein-coding gene on chromosome 2 (73,729,104 to 73,737,421, reverse strand). Ensembl gene ENSG00000144034.
Subcellular location: Cytoplasm, cytosol; Nucleus
Subcellular location (Human Protein Atlas): Cytosol
Pathways (Reactome):
Metabolism of RNA: tRNA modification in the nucleus and cytosol
Gene Ontology:
Molecular function: protein binding; protein kinase binding
Biological process: tRNA threonylcarbamoyladenosine modification; maintenance of translational fidelity
Cellular component: cytoplasm; cytosol; EKC/KEOPS complex; nucleus
Genetic constraint (gnomAD): Loss-of-function variants: 4 observed, 9.73 expected, observed/expected ratio (o/e) 0.41, 90% interval 0.2 to 0.94. That is too few expected variants to judge how well the gene tolerates losing a copy. Missense variants: 154 observed, 133.05 expected, observed/expected ratio (o/e) 1.16, 90% interval 1.01 to 1.32. Synonymous variants: 46 observed, 48.22 expected, observed/expected ratio (o/e) 0.95, 90% interval 0.75 to 1.22.
Homologues: Orthologues: chimpanzee TPRKB (99% identical), macaque TPRKB (98% identical), dog TPRKB (95% identical), pig TPRKB (91% identical), guinea pig TPRKB (90% identical), mouse Tprkb (85% identical), rat Tprkb (83% identical), zebrafish tprkb (57% identical), tropical clawed frog tprkb (50% identical), Caenorhabditis elegans W03F8.4 (36% identical).
Diseases named in the same sentence as TPRKB in open-access papers:
TPRKB is named in the same sentence as 13 diseases in open-access papers, as found by Europe PMC text mining. Sharing a sentence is not in itself a finding about the gene and the disease. The quoted sentences say what the papers report.
Galloway-Mowat syndrome (7 papers, 2018 to 2024). Galloway syndrome is characterized by the association of nephrotic syndrome and central nervous system anomalies. "Consanguineous families with homozygous missense mutations in TPRKB have been diagnosed with Galloway-Mowat syndrome-5 (OMIM #617731), in which affected people exhibit early-onset nephrotic syndrome, as well as dysmorphologies and delayed psychomotor development." (PMID 31451708, 2019). "The term “Galloway-Mowat syndrome 1 (GAMOS1)” is now used for GAMOS caused by mutations in WDR73, and “Galloway-Mowat syndrome 2-5 (GAMOS2-5)” is used for GAMOS with mutations in LAGE3, OSGEP, TP53RK, and TPRKB, respectively." (PMID 30558655, 2018). "We recently identified autosomal recessive mutations in genes encoding four of the five subunits of human KEOPS complex, namely LAGE3, OSGEP, TP53RK, and TPRKB in patients with Galloway-Mowat syndrome (GAMOS, OMIM#251300)." (PMID 31481669, 2019). "Galloway-Mowat syndrome (GAMOS) is a group of rare hereditary diseases by the combination of early onset steroid-resistant nephrotic syndrome (SRNS) and microcephaly with brain anomalies caused by WDR73, LAGE3, OSGEP, TP53RK, TPRKB, GON7, WDR4 or NUP133 mutations." (PMID 36755238, 2023). "For example, mutations in OSGEP, TP53RK, TPRKB, LAGE3 and C14orf142, encoding all five subunits of the human cytoplasmic KEOPS complex, lead to defective t6A modification and Galloway-Mowat syndrome (GAMOS), characterised by early-onset nephrotic syndrome, microcephaly and brain anomalies." (PMID 32047918, 2020).
epilepsy (1 paper, 2025). A brain disorder characterized by episodes of abnormally increased neuronal discharge resulting in transient episodes of sensory or motor neurological dysfunction, or psychic dysfunction. "Additionally, some genes (TPRKB, PRAG1, SLC25A12, and TRIM8) have been identified as associated with epilepsy, a neurological disorder characterized by recurrent seizures, that shares similar genetic vulnerability with SZ." (PMID 40282399, 2025).
cancer (2 papers, 2008 to 2021). A tumor composed of atypical neoplastic, often pleomorphic cells that invade other tissues. "Mutations of PRPK and TPRKB are found in human Galloway–Mowat syndrome and in various cancers." (PMID 33547416, 2021). "Genes encoding for proteins TPRKB, T-Complex 1 (TCP1), Olftactomedin 1 (OLFM1), LDOC1 and HTRA3 have been implicated positive or negatively in cancer progression." (PMID 18793431, 2008).
tumor (2 papers, 2021 to 2022). "So even though both groups of C-type cells have similar genomic mutation patterns, only cells that highly expressed TP53RK and TPRKB successfully metastasized to lymph node, which indicated that EKC/KEOPS complex may be beneficial for tumor metastasis." (PMID 35974387, 2022).
kidney disease (1 paper, 2019). "Variant analyses of patients 1 and 2 were performed by targeted massive parallel sequencing using an updated version of our kidney disease gene panel that includes more than 200 genes causative of or associated with inherited kidney diseases (including WDR73, TPRKB, TP53RK, LARGE3, and OSGEP genes)." (PMID 30975089, 2019).
TPRKB also shares sentences with these, for which no sentence is quoted: nephrotic syndrome (3 papers); microcephaly (2); brain disorder (1); Epileptic encephalopathy (1); fungal meningitis (1); hepatocellular carcinoma (1); neurological disorder (1); Primary microcephaly (1).